MSI1 (musashi RNA binding protein 1)
Diseases named in the same sentence as MSI1 in open-access papers (continued):
Sharing a sentence is not in itself a finding about the gene and the disease.
infection (6 papers, 2018 to 2026). The state of being infected such as from the introduction of a foreign agent such as serum, vaccine, antigenic substance or organism. "Using 2D cell cultures, stem cells, and 3D organoids, we show that depletion of Msi1 in intestinal cells augments infection." (PMID 41914497, 2026). "A panel of human cell lines that endogenously express MSI1 was subjected to infection with ZIKV and the corresponding pMBS1 mutant virus." (PMID 36854751, 2023). "More importantly, in BHK-21 cells that transiently expressed MSI1, RNA immunoprecipitation (RNA-IP) assays showed a remarkable reduction in the binding of MSI1 to viral RNA following ZIKV pMBS1m infection, compared to the WT virus." (PMID 36854751, 2023). "Compared to the mono-infection group, the RNA levels of miR-147 were significantly downregulated, whereas MSI1, KIAA1199, NF-κB p50, and EGFR were significantly upregulated in the bone marrow, livers, and hearts of chickens." (PMID 36291177, 2022). "Our findings show how translational repression of SARS-CoV-2 by stem cell RNA-binding proteins, such as Msi1, could help evade infection." (PMID 41914497, 2026). "MSI-1, thus, could be a potential candidate for drug development against infection induced by drug-resistant bacteria." (PMID 31938070, 2020). "Consequently, we focused on examining the expression of MSI1 during infection with CAstV and PEDV." (PMID 39936918, 2025). "To validate the results of the in vitro experiments, we detected the RNA levels of miR-147, MSI1, KIAA1199, NF-κB p50, and EGFR in the cancerous tissues of chickens in different infection groups, including the bone marrow, liver, and heart." (PMID 36291177, 2022). "Following infection by plus-strand RNA viruses such as avian leukosis virus subgroup J (ALV-J), reticuloendotheliosis virus (REV), chicken astrovirus (CAstV), and porcine epidemic diarrhea virus (PEDV), these viruses hijack MSI1 to relocate near and within the nucleus." (PMID 39936918, 2025). "In this study, intracellular RNase activity remained unchanged irrespective of infection with plus-strand RNA viruses or MSI1 overexpression, suggesting that viral RNA evaded cellular RNase degradation by interfering with intracellular RNase recognition after binding to MSI1." (PMID 39936918, 2025).
neurodegenerative disease (2 papers, 2019 to 2020). A disorder of the central nervous system characterized by gradual and progressive loss of neural tissue and neurologic function. "To evaluate the different levels and distributions of MSI1 and MSI2 amongst varying neurodegenerative diseases, we co-stained AD, ALS, FTD, aged Control brains MSI1 and MSI2 with anti-tau oligomeric monoclonal antibody (TOMA-2)." (PMID 32855391, 2020).
colon polyp (1 paper, 2017). "High levels of the intestinal stem-cell marker MSI1 have been observed in CD44+ colon polyp cells." (PMID 29110645, 2017).
kidney disease (1 paper, 2022). "Additionally, we also predated the enrichment of the RBPs associated with kidney disease including IGF2BP2 and MSI1 in the hypermethylated group." (PMID 35795641, 2022).
MSI1 also shares sentences with these, for which no sentence is quoted: adenocarcinoma (4 papers); amyotrophic lateral sclerosis (2); esophageal adenocarcinoma (2); acute lymphoblastic leukemia (1); adenomyosis (1); adenosquamous carcinoma (1); aneurysm (1); astrocytoma (1); breast (1); bronchioalveolar carcinoma (1); bronchioloalveolar carcinoma (1); cervical squamous cell carcinoma (1); cholangiocarcinoma (1); chronic gastritis (1); chronic obstructive pulmonary disease (1); co-infection (1); colitis (1); Diarrhea (1); dysplasia (1); embryonic carcinoma (1); ependymoma (1); esophageal cancer (1); gastritis (1); hematologic malignancies (1); inflammatory bowel disease (1); intestinal cancer (1); intestinal tumors (1); intrahepatic cholangiocarcinoma (1); irritable bowel syndrome (1); kidney cancer (1).
A further 28 diseases each share a sentence with MSI1 in 1 paper.